Y_RNA (Y RNA )
Gene: Miscellaneous RNA gene on chromosome 3 (106,515,897 to 106,515,998, forward strand). Ensembl gene ENSG00000200610.
Homologues: Orthologues: chimpanzee Y_RNA (99% identical), macaque Y_RNA (96% identical). Paralogues in human: Y_RNA (82% identical), Y_RNA (81% identical), Y_RNA (80% identical), Y_RNA (78% identical), Y_RNA (77% identical), Y_RNA (76% identical), RNY1P7 (75% identical), Y_RNA (75% identical), RNY1 (75% identical), Y_RNA (74% identical), Y_RNA (73% identical), RNY1P1 (72% identical), and 92 more.